ENSG00000287667 (novel transcript)
Gene: Long non-coding RNA gene on chromosome 4 (186,326,302 to 186,336,662, forward strand). Ensembl gene ENSG00000287667.
Gene Ontology:
Biological process: miRNA-mediated post-transcriptional gene silencing